PML (PML nuclear body scaffold)
Diseases named in the same sentence as PML in open-access papers (continued):
Sharing a sentence is not in itself a finding about the gene and the disease.
viral infection (continued). "Beyond its established functions in tumor suppression and apoptosis, PML proteins are increasingly recognized as modulators of inflammation, particularly in viral infections and innate immunity." (PMID 41439981, 2025). "HIRA is normally distributed throughout the nucleus, but under conditions of stress (such as viral infection, senescence, or interferon treatment) it is observed at PML-NBs." (PMID 41019635, 2025). "The promyelocytic leukemia (PML) gene is a general sensor of cellular stresses that include viral infections, oxidative stress, and DNA damage and promotes a variety of adaptive cell-protective responses (Lallemand-Breitenbach and de Thé, 2018)." (PMID 38730056, 2024). "For instance, PML knockdown enhances human immunodeficiency virus infection in fibroblast cells, but not in T cells or myeloid cell lines, highlighting the cell type-dependent functional roles of PML in virus infection." (PMID 38031162, 2023). "In summary, during AdV infection, PML NBs components are targeted by the virus as they mostly represent a barrier to viral infection." (PMID 37127643, 2023). "This study presents the first evidence that during JEV infection, both viral infection and innate immune responses are simultaneously suppressed in PML isoform-overexpressing cells." (PMID 38031162, 2023). "The H3.3 histone chaperone complex HIRA accumulates in PML NBs upon senescence, viral infection or IFN-I treatment in primary cells." (PMID 37227756, 2023). "PML isoforms play distinct roles in various biological processes, including their response to viral infections." (PMID 38031162, 2023). "Despite the considerable number of studies that have investigated the functions of the PML NBs in the context of viral infection, gaps in our understanding of the fine interactions between viruses and the very dynamic PML NBs remain." (PMID 37127643, 2023). "In conclusion, for PVs, it has been demonstrated that PML NB components mostly promote viral infection via several mechanisms." (PMID 37127643, 2023). "The abundance and integrity of PML NBs are challenged in a variety of physio-pathological conditions, ranging from oxidative stress to cancer or viral infections." (PMID 36175410, 2022). "In line with this, PML-NBs participate in the establishment of an IFN-induced antiviral state and depletion of PML reduces the capacity of IFNs to protect from viral infections." (PMID 35319461, 2022). "Daxx and Sp100, important components of PML-nuclear bodies, were also upregulated both directly by BoIFN-γand indirectly by viral infection." (PMID 36016774, 2022). "PML NBs are upregulated during several viral infections and are thought to have antiviral properties (Lallemand-Breitenbach and de Thé, 2010)." (PMID 34336833, 2021). "PML is an intrinsic restriction factor that counteracts viral infection by inhibiting viral replication." (PMID 34888375, 2021). "Cellular stress, viral infections, DNA damage, and oxidative stress modulate the regulation of PML NBs." (PMID 34336833, 2021). "Further studies are necessary to dissect how PML-NBs exert these complementary effects during viral infections." (PMID 33807177, 2021). "Most of these DEGs were associated with the host response to virus infection and type I interferons, while others such as IRF9, PML, IRF7, STAT1 and IFIH1 were related to interferon signaling." (PMID 33301474, 2020). "In contrast, increasing numbers of PML tracks led to decreasing distances from HAdV RCs in wt and mutant virus infections." (PMID 32184235, 2020). "Consistently, an increase in the number and size of PML-NBs was observed after viral infection and IFN treatment." (PMID 33343623, 2020). "The MERS-CoV-shared genes KRT6B and TNFAIP3 had a high p-value associated with SARS-CoV-2, whereas genes such as OAS1-3, IRF9, IRF7, STAT1, PML and IFIH1 were highly associated with host responses to viral infections and type I interferon." (PMID 33301474, 2020).
viral infection (continued). "PML bodies have fascinated cell biologists and molecular virologists due to their beauty and apparent involvement in many cellular processes including viral infection." (PMID 32365141, 2020). "ICP0 localizes to PML NBs at early times of viral infection and was shown to disrupt and reorganize PML NBs, mainly by mediating the degradation of specific PML isoforms." (PMID 32154186, 2020). "Viral infection has been used extensively to study the roles of PML NBs in innate immune signaling as repressors of viral gene expression and coregulators of interferon (IFN) responses." (PMID 32154186, 2020). "Intrinsic immunity to viral infection involves translocation of PML NB components to the nuclear periphery to inhibit viral replication." (PMID 30745338, 2019). "ChIP-seq analysis revealed that PML, the principle scaffolding protein of PML-NBs, was required for the enrichment of HIRA onto ISGs, identifying a role for PML in the HIRA-dependent regulation of innate immunity to virus infection." (PMID 30901352, 2019). "The use of such mutants has been critical for the characterization of many aspects relating to the antiviral roles of PML-NBs in the regulation of intracellular immunity during virus infection." (PMID 30901352, 2019). "Significantly, the composition and morphology of PML-NBs can vary in response to cellular stress and virus infection, consistent with PML-NBs playing a role in key cellular functions, including the antiviral response." (PMID 31456950, 2019). "PML NB size, number, content, and distribution are controlled by many factors, such as type I and II interferons, cellular stress, DNA damage, and viral infections (32, –, 39)." (PMID 29669885, 2018). "PML is an interferon-inducible TRIM protein that can restrict viral infection (Everett and Chelbi-Alix, 2007, Kalejta, 2008, Tavalai and Stamminger, 2011)." (PMID 30021158, 2018). "Since PML has dual function in the defense of viral infection and tumor suppression, it has been proposed that PML participates in the virus-induced tumorigenesis." (PMID 29416846, 2018). "One major function of PML against viral infection is to sequester viral core components required for viral replication." (PMID 29416846, 2018). "During numerous nuclear replicating virus infections, several nuclear domains have been shown to be targeted by viral proteins, such as nucleoli, promyelocytic leukemia (PML) bodies, and nuclear speckles (18, –, 21)." (PMID 30209172, 2018). "A recent study further elucidated the connection between viral infection and PML-mediated IFN stimulated gene regulation." (PMID 29416846, 2018). "PML NBs are disrupted upon viral infection and PML expression is induced in response to inflammation, suggesting its role in the anti-viral defense system." (PMID 29416846, 2018). "PML bodies participate in the intrinsic cellular defense against virus infection and are rapidly dispersed upon induction of the productive cycle." (PMID 28414785, 2017). "These events generate an unprecedented situation compared to several viral infections that induce PML degradation and/or PML NB disruption to counteract PML antiviral activity." (PMID 28074026, 2017). "One such ISG that is known to promote both intrinsic and innate responses to viral infection is the product of the promyelocytic leukemia (PML) gene." (PMID 28628648, 2017). "Proteasome-mediated degradation of promyelocytic leukemia tumor suppressor (PML) is upregulated in many viral infections and cancers." (PMID 27058621, 2016). "Since their discovery, PML bodies have been demonstrated to play central roles in regulating apoptosis, DNA damage repair, transcription, and viral infection." (PMID 25665578, 2015). "PML nuclear bodies (PML-NBs) are dynamic subnuclear structures that coordinate immune signaling programs and have a demonstrated role in controlling viral infection." (PMID 25848798, 2015).
viral infection (continued). "On shC cells, incubation with 4 μM arsenite enhanced viral infection by 2.4-fold and up to the level of viral infectivity on shPML-expressing HFFs, suggesting that the shRNA-mediated knockdown of PML can indeed be mimicked by sodium arsenite treatment." (PMID 26703718, 2015). "IE1 is not essential for viral replication, but enhances replication by targeting intrinsic barriers to viral infection (PML-bodies, hDaxx, STAT-2, and p107), whereas IE2 is essential and is a potent transcriptional transactivator." (PMID 24787765, 2014). "This is the first demonstration of the implication of PML in the enhancement of IFN-β production upon viral infection." (PMID 24586174, 2014). "PML-NB components act as a barrier against many viral infections; however, viral antagonistic proteins have evolved to modify PML-NBs, thus abrogating this cellular defense." (PMID 25412268, 2014). "We are looking forward to these developments with the expectation that pharmacologic targeting of the networks that control PML degradation will lead to specific therapies for cancer and for several viral infections." (PMID 23526763, 2013). "Several viral proteins have been identified that promote viral infection by disrupting PML nuclear bodies either by interfering with the interactions of PML proteins to form the bodies or by inducing the degradation of the PML proteins." (PMID 23170171, 2012). "PML-NBs are probably the most thoroughly studied nuclear domains in the context of virus infection for their involvement in the innate antiviral response and in the interferon (IFN) response pathway." (PMID 22912575, 2012). "One key function of PML is to protect cells from viral infection and SUMOylation also regulates PML’s anti-viral activities." (PMID 23316480, 2012). "In recent years, nuclear domain 10 (ND10), also called PML bodies, has been a topic of intense interest, especially in terms of its role in viral infection." (PMID 21552525, 2011). "The size and abundance of PML-NB is interferon inducible, and over-expression of the PML protein represses viral infection." (PMID 22102817, 2011). "The inhibitory effects of ND10 proteins on viral infection have been demonstrated on PML, Daxx, and SP100." (PMID 21552525, 2011). "The most important ND10 proteins include SP100, Daxx, and PML, all of which have been demonstrated to be intrinsic defense mechanisms against viral infection." (PMID 21552525, 2011). "While several viral proteins are known to promote lytic viral infection through disruption of PML NBs, our results indicate that viral proteins can also contribute to carcinogenesis through PML disruption." (PMID 18833293, 2008). "Our analysis revealed that TRIM19 (PML), 21, 22, 25, 31, and 69 could interact with genes or proteins that play key roles in viral infections, responses to IFNs, and cytokine-mediated responses." (PMID 38932287, 2024). "Aberrant cytoplasmic localization of PML has been noted in viral infections and cancer." (PMID 39395810, 2024). "The interplay between PML and PML-NBs with virus infection is complex." (PMID 38031162, 2023). "Although HIRA complex is diffusively distributed in the nuclei of proliferating somatic cells, it accumulates in PML NBs upon various stresses such as senescence entry, viral infection, or interferon type I (IFN-I) treatment, which encompasses IFNα and IFNβ cytokines." (PMID 37227756, 2023). "PML is an important host restriction factor for multiple viral infections." (PMID 38031162, 2023). "Increasing evidence has shown that PML isoforms use their specific C-terminus to interact with different proteins and carry out isoform-specific functions in gene regulation, tumor suppression, and virus infection." (PMID 37243155, 2023). "Furthermore, ATRX represents a component of PML nuclear bodies (PML-NBs) which are considered as enigmatic nuclear protein accumulations exhibiting a tight link to cell-intrinsic restriction of viral infections." (PMID 35939517, 2022).
viral infection (continued). "The membrane-less property of PML-NBs facilitates the dynamic flux and interactions of PML-NB client molecules, which have been shown to be involved in a number of biological processes, including viral infection, DNA damage response, senescence, and telomere recombination." (PMID 35579421, 2022). "PML-NBs are dynamic organelles in the nucleus that are formed by the key component PML as well as multiple other proteins and play an important role in intrinsic immunity against viral infections." (PMID 35939517, 2022). "ATO is therefore of translational interest to modulate PML NB functions during viral infections." (PMID 33807177, 2021). "The interplay between PML NBs and viral infection is multifaceted." (PMID 34513832, 2021). "In addition, the number of PML-NBs was significantly increased after JEV infection, suggesting that the components and morphology of PML-NBs vary in response to virus infection." (PMID 34888375, 2021). "Consequently, the biological role of PML-NBs during virus infection has been extensively studied, which has revealed these discrete nuclear substructures to play an important function in the spatiotemporal regulation of host immune defences to virus infection." (PMID 32416261, 2020). "PML-NBs are highly dynamic nuclear substructures composed of more than 70 proteins that respond to a variety of stimuli, including heat shock, cytokine signalling, and virus infection." (PMID 32416261, 2020). "This study also provides initial evidence for the idea that disruption of PML bodies upon viral infection is linked to activation rather than inhibition of innate immunity." (PMID 32365141, 2020). "Our findings challenge current views regarding the role of PML bodies in viral infection." (PMID 32365141, 2020). "New microscopy techniques, particularly high-resolution microscopy and three-dimensional reconstruction of images, have greatly advanced our way of studying PML NBs in recent years, and thus have led to better understanding of their role in the context of viral infection." (PMID 32154186, 2020). "Automated quantitation of PML NBs using immunofluorescence staining of PML and SP100 proteins revealed that the resistant ATRX-deficient/ALT cell lines contain more PML NBs than cell lines that were sensitive to mutant virus infection." (PMID 30745338, 2019). "Clearly, irrespective of whether PML can be formally delineated as a host restriction factor for viral infection in this context, PML is clearly an interesting candidate for the development of future therapies against DENV and potentially other flaviviruses." (PMID 31456950, 2019). "While PML bodies appear to be relatively stable in the nuclei of unperturbed healthy cells, they have the potential to undergo dramatic rearrangements under circumstances where cells are exposed to virus infection or various types of stressors." (PMID 31416160, 2019). "A pivotal cellular protein in the host response to viral infection is PML." (PMID 30021158, 2018). "In addition to its role in anti-bacteria or -viral infection, PML also participates in innate and adaptive immunity." (PMID 29416846, 2018). "This echoes the intrinsic antiviral activities of PML in the context of viral infections." (PMID 28074026, 2017). "In addition, it became evident in recent years that PML-NBs also contribute substantially to the intrinsic immunity to viral infection, in particular to infection by DNA viruses." (PMID 29065450, 2017). "PML-NBs are implicated in multiple cell processes, such as apoptosis, senescence andaging, but also act as nuclear sensors of multiple stresses including viral infections.Indeed, PML-NBs have been shown to negatively regulate the infection by DNA and RNAviruses." (PMID 28357326, 2016).
viral infection (continued). "More specifically, the overexpression of PML-VI augmented the production of IFNβ in U373-MG or HeLa cells stimulated by double RNA or virus infection, and this augmentation was attributed to the ability of PML-VI to recruit Pin1 to PML NBs, and thereby prevent the degradation of phosphorylated IRF3." (PMID 25812002, 2015). "The activation of IRF3 after virus infection was comparable in control and PML-knockdown HF cells." (PMID 25812002, 2015). "An examination of these, as well as a number of other reported sites in the literature, revealed that only those in the phospho-SIM motif appear to play a significant role in either the ability of PML to alter ND10 morphology or formation or in its response to viral infection." (PMID 25513827, 2014). "We are the first group to examine PML phosphorylation during viral infection." (PMID 25513827, 2014). "PML SUMOylation is enhanced by various stimuli including As2O3 treatment and viral infections." (PMID 23734343, 2013). "Viral infections often result in PML-NBs disruption and PML degradation." (PMID 23526763, 2013). "The promyelocytic leukemia tumor suppressor gene (PML) critically regulates several cellular functions that oppose tumorigenesis such as oncogene-induced senescence, apoptosis, the response to DNA damage and to viral infections." (PMID 23526763, 2013). "In addition to the PML NB disruption that occurs upon viral infection or in APL cells, expression of the PML protein is frequently lost in human cancers from multiple origins." (PMID 23734343, 2013). "One key function of the PML NBs is to protect cells from viral infection." (PMID 23734343, 2013). "In addition, PML proteins are induced as part of the innate antiviral response and suppress productive viral infection in multiple ways." (PMID 23170171, 2012). "Furthermore, class I HLAs are often down-regulated by virus infection, consistent with the notion that PML is an anti-viral protein." (PMID 22947142, 2012). "Additionally, promyelocytic leukemia protein (PML) is a well-known tumor suppressor that is involved in various cellular processes including apoptosis, viral infection, senescence, DNA damage repair, and cell cycle regulation but is frequently mutated in cancers." (PMID 33807199, 2021). "Although PML bodies appear relatively stable and immobile in most cells under normal physiological conditions, they are also known for their ability to change their morphology and protein composition in response to cell cycle progression, virus infection or various stress stimuli." (PMID 31416160, 2019). "Therefore, the interaction of endogenous Pin1 with SUMOylated PMLIV and its recruitment in PML NBs could alter Pin1-induced downregulation of activated IRF3 thus resulting in a higher amount of phosphorylated IRF3 during viral infection." (PMID 24586174, 2014). "However, it is unclear whether this PML isoform specificity also applies to other types of viral infection." (PMID 23761861, 2013). "Moreover, PML downregulation plays an important role in promoting viral infections." (PMID 23526763, 2013). "Thus, a better understanding of the molecular mechanisms involved in virus-dependent PML degradation may provide new insight in a more efficient antiviral therapies or strategies to prevent viral infections." (PMID 23526763, 2013). "Finally, future studies should further assess the influence of PML on inflammasome activation in specific disease-relevant cell and animal models to better understand the clinical relevance of these findings in different disease contexts such as atherosclerosis, sepsis or viral infections." (PMID 41439981, 2025). "Following virus infection, we utilized JEV E protein antibody and PML antibody for dual staining and confocal laser photography, subsequently counting the number of PML-NBs in JEV antigen-positive cells and viral antigen-negative cells." (PMID 37928180, 2023).